YTHDF2 (YTH N6-methyladenosine RNA binding protein F2)
Diseases named in the same sentence as YTHDF2 in open-access papers (continued):
Sharing a sentence is not in itself a finding about the gene and the disease.
tumor (continued). "The GO enrichment analysis of the combined two data sets showed that “regulation of mRNA metabolic process” and “RNA splicing” are the top two enriched pathways, which might involve in the YTHDF2-regulated tumor development and progression." (PMID 36120577, 2022). "Single-cell sequencing analyses revealed that expression of YTHDF2 could be detected not only in malignant tumor cells, but also in the surrounding immune cells." (PMID 36120577, 2022). "YTHDF2 is also diminished and acts as a tumor suppressor in other malignant tumors." (PMID 35382893, 2022). "YTHDF2 exhibits tumour oncogenic and cisplatin‐desensitising properties, which may offer insight into the development of novel combination therapeutic strategies for ICC." (PMID 35696608, 2022). "However, TCGA-KIRC database found comparable levels of YTHDF2 in tumor versus normal tissues in ccRCC." (PMID 35637958, 2022). "Additionally, histone Kla regulates the transcription of tumor-related genes such as YTHDF2, which promotes tumor growth, metastasis, and invasion by encouraging the degradation of downstream tumor suppressors." (PMID 36050306, 2022). "As both the m6A writer METTL3 and the reader YTHDF2 positively regulate the anti-tumor immunity of NK cells, METTL3- and YTHDF2-mediated m6A methylation might be important regulators of anti-tumor immunity and homeostasis of NK cells." (PMID 35296338, 2022). "YTHDF2 could accelerate tumor growth by combining with tumor suppressors to trigger a downstream cascade, while it could exert the opposite effect by interacting with oncogenes." (PMID 35382893, 2022). "Our study revealed abnormally high YTHDF2 expression in tumour tissues." (PMID 35186724, 2022). "YTHDF2 knockdown significantly inhibited tumour growth in HuCC‐T1 xenograft models." (PMID 35696608, 2022). "As for YTHDF2, tumor purity, B cells, CD8 + T cells, and neutrophils showed a strong correlation." (PMID 35148766, 2022). "Because the migration and invasion of cells are closely related to the metastasis and progression of malignant disease, we speculate that YTHDF2 may play an important role in tumour metastasis." (PMID 35186724, 2022). "Besides, studies have found that YTHDF2 facilitated malignant progression in several cancers, including early NSCLC; in this case, its elevated expression was linked with tumor growth and metastasis." (PMID 35924072, 2022). "Low YTHDF1 or YTHDF2 reflects an immune hot tumor signature and may serve as a predictor or prognostic marker." (PMID 36479088, 2022). "In addition, the m6A methylation-binding protein YTHDF2 was found to affect tumor growth in mice through the YTHDF2-MYC-IGFBP3 pathway, providing a new target for the treatment of GBM." (PMID 36118889, 2022). "In vivo assays, the role of YTHDF2 in tumor growth was further uncovered." (PMID 34996459, 2022). "Recent studies demonstrated a novel tumor-promoting effect of YTHDF2 by analyzing its upstream signal in the OC and showed that the chemical modification of m6A as a signal center could interact with important metabolic pathways." (PMID 36371254, 2022). "In addition, the co-expression of YTHDF2 and immune cell-related genes in those cancer types further confirmed the correlation between YTHDF2 and tumor immune infiltration." (PMID 36120577, 2022). "YTHDF2 might function as a tumor suppressor through inhibiting cell growth and proliferation in HCC." (PMID 36120577, 2022). "In addition, the combination treatment of YTHDF2 siRNA and cisplatin significantly enhanced the anti‐tumour effect of cisplatin in a chemoresistant ICC PDX model." (PMID 35696608, 2022). "The positive expression of YTHDF2 could restrain cell proliferation and tumor growth in mouse xenografts." (PMID 35382893, 2022). "Beyond METTL3 loss, a deficiency in Mettl14 or Ythdf2 in macrophages promotes the accumulation of EBI3 mRNA in an m6A-dependent manner, thereby triggering CD8+ T cell dysfunction, preventing CD8+ T cell infiltration, and accelerating tumor progression." (PMID 35254013, 2022).
tumor (continued). "The literature also shows very different roles for YTHDF2 in different tumour types." (PMID 35186724, 2022). "In short, YTHDF2 might serve as a potential biomarker for tumor detection, therapeutic response and prognostic analysis." (PMID 36120577, 2022). "It is of interest that there are two aspects to the regulatory role of YTHDF2 in tumor immunity." (PMID 36017491, 2022). "In addition, YTHDF2 was found to be abnormally overexpressed in lung cancer, where it promoted the translation of 6-phosphogluconate dehydrogenase to support tumor growth." (PMID 36360287, 2022). "However, YTHDF2 functioned as a tumor suppressor in HCC via destabilization of epidermal growth factor receptor (EGFR) mRNA89, leading to the inhibition of the ERK/MEK signaling pathway in HCC." (PMID 36446846, 2022). "Although the role of YTHDF1 or YTHDF2 in the tumor immune microenvironment may differ depending on cell type, no such study has been performed." (PMID 36479088, 2022). "In addition, we also found a positive correlation between the CNVs of YTHDF2 and the tumor infiltrating lymphocytes (TILs), immunostimulants, immunosuppressants, MHC, chemokines, and chemokine receptors, especially in CHOL, KICH, and LGG." (PMID 36120577, 2022). "Our results showed that the expression of YTHDF2 was negatively correlated with estimate scores, stromal scores, and immune scores in human generalized cancers, but positively correlated with tumor purity in the majority of tumor types, suggesting an important role of YTHDF2 in TME composition." (PMID 36120577, 2022). "Finally, we confirmed that YTHDF2 was highly expressed in LGGs tissues and correlated with the tumor grade with immunohistochemistry assay." (PMID 35661004, 2022). "In NSCLC, the expression of YTHDF1 is higher in tumor tissues than in normal tissues, while the expression of YTHDF2 is lower in tumor tissues than in normal tissues, indicating that YTHDF1 is more likely to bind to methylated YAP1 mRNA to promote its translation." (PMID 35063010, 2022). "Phosphoinositide-3-kinase catalytic beta (PI3KCB), a catalytic subunit of PI3K, was reported to be modified by m6A resulting in its degradation, which was caused by YTHDF2, and subsequently inhibited the activation of PI3K/AKT signaling pathway to limit tumor progression." (PMID 35382893, 2022). "While YTHDF2, RBM15, ZC3H13, METTL3, HNRNPC, YTHDC1 with m6a modifications had higher expression in the low risk group, indicating that they might be tumor suppressors." (PMID 36199800, 2022). "After identifying the expression of YTHDF2 was regulated by H3K18la, we would like to determine whether histone lactylation induced tumor suppression could be rescued by gain of YTHDF2." (PMID 33726814, 2021). "YTHDF2 can influence tumor progression in several different ways." (PMID 33795663, 2021). "Despite its known role in tumour progression, the expression, regulation and specific biological function of YTHDF2 in CRC remain unclear." (PMID 34709763, 2021). "However, some research indicates that YTHDF2 suppresses tumor progression in Hepatocellular carcinomas and osteosarcomas." (PMID 34512342, 2021). "In addition, we observed that YTHDF2 knockdown inhibited tumor cell colony formation and migration, as measured by plate colony formation assays and transwell assay, respectively." (PMID 33726814, 2021). "This was the first report indicating that YTHDF2 might act as a tumor suppressor to suppress cell proliferation and growth by destabilizing EGFR mRNA in HCC development." (PMID 34421350, 2021). "Moreover, depletion of YTHDF2 prolonged the survival of tumor-bearing mice as compared with the control, whereas LXRα and HIVEP2 knockdown reversed the effect of YTHDF2 depletion on the survival of tumor-bearing mice." (PMID 33420027, 2021). "As a result, we hypothesized that YTHDF2 could influence tumor immunology and serve as an immunotherapeutic target for KIRC therapy." (PMID 34512342, 2021).
tumor (continued). "Finally, we also validate the role of YTHDF2 in promoting tumor progression and activating NF-κB signaling in orthotopic xenograft models." (PMID 34246306, 2021). "m6A RNA modification through YTHDF2-mediated EGFR degradation plays a role in tumor suppression." (PMID 34660577, 2021). "In addition, YTHDF2 knockdown significantly inhibited tumorigenesis in a murine tumor xenograft model." (PMID 33980824, 2021). "In addition, FTO catalyzes the demethylation of HOXB13 mRNA in the 3′UTR region, thereby eliminating the recognition of YTHDF2 protein-modified m6A that affects tumor metastasis." (PMID 34660577, 2021). "Functioning as a tumor suppressor, high level of YTHDF2 could inhibit the proliferation and neoplasia by degrading EGFR mRNA of HCC cells in an m6A-dependent manner." (PMID 34747720, 2021). "In contrast, some researches indicated that YTHDF2 severed as a tumor suppressor in HCC." (PMID 33593354, 2021). "This review summarized the current researches and concluded that YTHDF2 played an oncogenic role or acted as a tumor suppresser by regulating tumor cell proliferation, survival, growth, apoptosis, cell cycle, migration, invasion, metastasis, cell viability and so on." (PMID 33593354, 2021). "Moreover, YTHDF2-depleted tumors displayed distinct margins with significantly reduced invasive fingers of tumor." (PMID 33420027, 2021). "This indicates that, contrary to LINC00022 and FTO, YTHDF2 plays a tumor suppressor role in ESCC." (PMID 34544449, 2021). "YTHDF2 can also inhibit HCC tumor cells and related vessels by processing IL11 and SERPINE2 mRNAs." (PMID 34105069, 2021). "We found higher protein and mRNA expression of TRMT6, TRMT10C and YTHDF2 in tumor samples." (PMID 34777359, 2021). "YTHDF2 is also considered as a potential suppressor of tumor immunity." (PMID 34956201, 2021). "To confirm this hypothesis, we first determined the protein levels of YTHDF2 in 14 pairs of ESCC tumor specimens and the matched normal specimens by Western blot, and found that YTHDF2 was decreased in 13 of the 14 cases of ESCC tumors." (PMID 34544449, 2021). "Furthermore, YTHDF2 was found to be upregulated in lung cancer, and to aberrantly promote the translation of 6PGD mRNA which is critical for the promotion of tumour growth." (PMID 33461542, 2021). "On the contrary, YTHDF2 was reported to function as a tumor suppressor in other studies, YTHDF2 inhibited the proliferation and growth of HCC cells via promoting the degradation of epidermal growth factor receptor (EGFR) mRNA, which is the upstream of the ERK/MAPK pathway." (PMID 33928028, 2021). "Taken together, our data indicated that YTHDF2 acts as a tumor promoter in LUAD." (PMID 33980824, 2021). "YTHDF2 shows higher protein expression in tumor relative to adjacent non-tumor tissue." (PMID 33420027, 2021). "Most increased regulators in tumor cases compared to normal cases were YTHDF2 (p < 0.001), FTO (p < 0.001), YTHDC1 (p < 0.001), YTHDC2 (p < 0.001), YTHDF1 (p < 0.001), KIAA1429 (p < 0.001), METTL3 (p < 0.010), WTAP (p < 0.001), RBM15 (p < 0.001), HNRNPC (p < 0.001), and ALKBH5 (p = 0.001)." (PMID 32733931, 2020). "In addition, histochemical staining of the tumor confirmed the low expression of YTHDF2 in the tumor tissue." (PMID 33505426, 2020). "Similarly, the expression of YTHDF2 was higher in grade 3 LGG than in grade 2, and high YTHDF2 expression was a prognostic factor in LGG with different tumor grades." (PMID 32986017, 2020). "In summary, knocking down YTHDF2 dramatically inhibited the tumor growth and metastasis in vivo." (PMID 33121495, 2020). "Thus, in this study we found that YTHDF2 as a crucial m6A reader exerted its degradation function by targeting two tumor suppressors LHPP and NKX3–1, consequently inducing AKT phosphorylation in PCa." (PMID 33121495, 2020). "However, in HCC, hypoxia induces the reduction of YTHDF2, which promoted tumor inflammation and angiogenesis." (PMID 32733807, 2020).
tumor (continued). "In addition, YTHDF2 protein levels were gradually decreasing with the increasing grade of NSCLC tumor." (PMID 32106857, 2020). "Therefore, the roles of YTHDF2 in cancer remain elusive, especially regarding tumor-immune interactions." (PMID 32986017, 2020). "In addition, YTHDF2 acted as a tumor oncogene to promote prostate cancer cell proliferation and migration." (PMID 32986017, 2020). "Besides, YTHDF2 can suppress tumor growth through modulating the m6A methylation of EGFR mRNA by the m6A/mRNA degradation pathway." (PMID 33015074, 2020). "However, YTHDF2 effects on the prognosis of different tumors and correlation with tumor immune infiltration are unclear." (PMID 32986017, 2020). "Finally, the correlation between YTHDF2 and infiltration of immune cells was studied in the tumor environment via the Tumor Immune Estimation Resource (TIMER) database." (PMID 33344502, 2020). "In addition, YTHDF2 expression positively correlated with expression of several immune cell markers, including PD-1, TIM-3, and CTLA-4, as well as tumor-associated macrophage gene markers, and isocitrate dehydrogenase 1 in LGG." (PMID 32986017, 2020). "Moreover, YTHDF2 expression in ccRCC tissues (N = 529) is significantly lower than that of tumor-adjacent normal tissues (N = 72, P = 0.0086)." (PMID 33102202, 2020). "Specifically, the expression of YTHDF2 was higher in normal tissues than in tumor tissues." (PMID 32106857, 2020). "We focused on the relationship between YTHDF2 and marker genes of various types of immune cells [CD8+ T cells, monocytes, T cells (general), M1 and M2 macrophages, B cells, neutrophils, tumor-associated macrophages (TAMs), natural killer cells, AND DCs] in LIHC in GEPIA and TIMER databases." (PMID 33344502, 2020). "And the results indicated that knock-down of NKX3–1 and LHPP could significantly induced the tumor growth, but knock down of YTHDF2 or METTL3 partially rescued the mice tumor growth induced by knock down of LHPP and NKX3–1." (PMID 33121495, 2020). "Furthermore, KDM5A was found to downregulate MOB3B expression, consequently augmenting PCa cell proliferation, migration and invasion in vitro and promoting tumor growth in vivo via the miR-495/YTHDF2 axis." (PMID 33087165, 2020). "We verified YTHDF2 protein levels were also decreased in hypoxic cells and tumor specimens." (PMID 31735169, 2019). "Notably, YTHDF2 mRNA was reduced in both hypoxic cells and tumor tissues, which indicated an inverse correlation with the m6A/A ratio." (PMID 31735169, 2019). "Recent reports referred YTHDF2 was able to degrade both tumor promoter and suppressor gene mRNAs." (PMID 31735169, 2019). "Here we identify YTHDF2 as a novel tumor suppressor resolving cancer-promoting inflammation." (PMID 31735169, 2019). "Notably, we also observed a potential association between YTHDF2 expression and lymph node metastasis, suggesting that YTHDF2 may contribute to the promotion of tumor metastasis." (PMID 41323282, 2025). "Therefore, YTHDF2 affects tumor cell survival and death by regulating TAM function." (PMID 39802639, 2025). "YTHDF2, an m6A reader, is pivotal in many cellular processes, including but not limited to migration, invasion, metastasis, proliferation, apoptosis, cell cycle regulation, viability, adhesion, differentiation, and inflammation, across various neoplastic diseases." (PMID 39802639, 2025). "Current research has demonstrated that YTHDF2 may act as both a tumor suppressor and an oncogene." (PMID 41369154, 2025). "Thus, targeting YTHDF2 may help reprogram the tumor immune microenvironment and enhance the efficacy of ICIs." (PMID 41403953, 2025). "Second, the field needs systematic testing whether targeting specific m6A nodes (e.g., YTHDF2 in TAMs or IGF2BP2/3 at the tumor–endothelium interface) leads to vessel normalization and improved antigen trafficking—alone or combined with anti-VEGF and checkpoint blockade." (PMID 41280938, 2025).
tumor (continued). "Furthermore, the absence of YTHDF2 in tumor-associated macrophages (TAMs) impedes tumor growth by reprogramming TAMs to an antitumor phenotype and enhancing their capacity to cross-present antigens." (PMID 39593172, 2024). "In addition, YTHDF2 may act as a tumor suppressor to repress cell proliferation and growth by destabilizing EGFR mRNA in HCC cells." (PMID 36936652, 2023). "Furthermore, YTHDF2 has been reported to exert dual functions in an m6A-dependent manner relying on whether the downstream target genes are tumor-promoting or tumor-suppressing." (PMID 36870954, 2023). "Therefore, YTHDF2 not only enhances immunity but also promotes tumor immune escape, which are functions that may depend on differences in tumor types and the mechanisms of tumorigenesis." (PMID 36017491, 2022). "Therefore, YTHDF1 deletion may enhance antitumor immunity by facilitating interactions with DCs, rather than promoting their differentiation and proliferation, supporting a potential role of YTHDF2 as a tumor immunosuppressive factor." (PMID 35794625, 2022). "Indeed, it has been shown that YTHDF2 is associated with breast cancer since it can recognize the m6A sites of the BNIP3 mRNA that encodes for an apoptotic protein which induces cell death, and causes its degradation, hence the promotion of tumor growth." (PMID 35327559, 2022). "Additionally, the YTHDF2 expression level was increased with the tumor grade elevated." (PMID 35661004, 2022). "Moreover, YTHDF2 might participate in the immune regulation through influencing the expression of immune checkpoint genes and the infiltration of immunocytes in tumor microenvironment." (PMID 36120577, 2022). "YTHDF2, as a tumor promoter, may lead to a poor prognosis for LUSC patients." (PMID 34996459, 2022). "However, as a tumor suppressor in EC, YTHDF2 can inhibit the tumorigenicity of EC." (PMID 35813486, 2022). "Therefore, YTHDF2 was found to act as a tumor-promoting factor in PCa." (PMID 35382893, 2022). "In a study of NSCLC, YTHDF1 and YTHDF2 were associated with a good prognosis of NSCLC patients, and down-regulation of YTHDF1 and YTHDF2 could up-regulate the expression of PD-L1 and reverse the tumor suppressive microenvironment." (PMID 36618420, 2022). "Thus, YTHDF2 may function by regulating the expression of target genes to influence tumor development." (PMID 35382893, 2022). "Given that the Wnt/β-catenin signaling pathway is related to cancer cell proliferation and migration, we hypothesized that the deprivation of the m6A methylation reader YTHDF2 might inhibit tumor growth and migration via the inactivation of the Wnt/β-catenin signaling pathway." (PMID 33980824, 2021). "However, reports have also shown that YTHDF1 and YTHDF2 can act as tumor suppressors." (PMID 33922187, 2021). "Considering that there are numerous m6A-modified tumor-related mRNAs and opposite roles of m6A binding proteins (YTHDF2 and IGF2BPs), the dysregulation of m6A installation could disrupt the homeostasis of post-transcriptional gene expression, thereby leading to oncogenic function in cancerogenesis." (PMID 34272618, 2021). "Furthermore, depletion of YTHDF2 prolonged the survival of tumor-bearing mice." (PMID 33420027, 2021). "Moreover, when S39A/T381A mutant was expressed to a similar amount as wild-type YTHDF2 (judged by the similar mRNA levels), it displayed minimal effects on the promotion of invasiveness of LN229 cells, proliferation of GSC11 and GSC7-2 cells, and tumor growth compared with wild-type YTHDF2." (PMID 33420027, 2021). "Moreover, YTHDF2 may function as a tumor suppressor to inhibit cell proliferation and growth in HCC." (PMID 32986017, 2020). "Whether YTHDF2 is a driving factor mediating DCs and tumor metastases merits further study." (PMID 33344502, 2020). "Hence, in the tumor microenvironment, YTHDF2 has an important role in immune escape." (PMID 33344502, 2020).